SOCS3 (suppressor of cytokine signaling 3)
Diseases named in the same sentence as SOCS3 in open-access papers (continued):
Sharing a sentence is not in itself a finding about the gene and the disease.
breast cancer (continued). "miR-9 and miR-181a in exosomes derived from breast cancer were identified to target SOCS3 and PIAS3, respectively, and further activated the JAK/STAT pathway, thus promoting the amplification and development of eMDSC." (PMID 35634311, 2022). "miR-9 was also identified as activating the JAK/STAT pathway via targeting SOCS3 and promoted the development of eMDSCs in breast cancer." (PMID 35634311, 2022). "Suppressor cytokine signal 3 (SOCS3) is one of the most important tumor suppressors in inhibiting breast cancer cells by regulating inflammatory factors, strengthening the immune system, and invoking immune cells." (PMID 35928368, 2022). "SOCS3 is involved in the pathobiology of prostate cancer, ulcerative colitis, breast cancer and atopic asthma/dermatitis." (PMID 34349769, 2021). "Inhibition of miR-203 represses ER+ breast cancer proliferation, growth and self-renewal capacity of BCSCs by negatively regulating suppressor of cytokine signaling 3 (SOCS3) expression." (PMID 33413418, 2021). "Higher expression levels of SOCS1, SOCS3, SOCS4, and SOCS7 have all been reported to associate with better prognosis in human breast cancer." (PMID 33758600, 2021). "DANCR induced down‐regulation of SOCS3‐induced inflammatory response and multiple malignant phenotypes in breast cancer cell." (PMID 31860165, 2020). "Lastly, on the molecular level, the activities of DANCR in normal, early‐ or late‐stage breast cancer cells were achieved by EZH2‐mediated epigenetic down‐regulation of SOCS3." (PMID 31860165, 2020). "CircTADA2A-E6 restores the cellular level of SOCS3 to the normal that is frequently downregulated in breast cancer." (PMID 31597272, 2019). "SOCS3 can be also detected in breast cancer tissue samples because the number of analyzed samples is relatively small (3 normal breast tissues, 6 in situ ductal carcinomas, and 11 infiltrating ductal carcinomas)." (PMID 28228755, 2017). "Recent studies have revealed SOCS3 overexpression can inhibit cell proliferation and anchorage-independent growth in breast cancer cells, whereas down-regulation of SOCS3 reflects a poor prognosis in gastric cancer and hepatocellular carcinoma." (PMID 28743280, 2017). "We found that more MDSCs were recruited in IL-6 high-expressing breast cancer tissues, in which SOCS3 inhibition was detected." (PMID 29326716, 2017). "Dehydrocostus lactone, a plant-derived sesquiterpene lactone, inhibits cell proliferation by inducing cell cycle arrest and apoptosis through upregulating SOCS1 and SOCS3 in breast cancer cells." (PMID 28228755, 2017). "Mechanistically, we discovered that activated FXR counteracts leptin action on breast cancer cells through its ability to induce the expression of the suppressor of cytokine signaling 3 (SOCS3), a prototype molecule of the SOCS family." (PMID 26899873, 2016). "The direct involvement of activated FXR in the regulation of SOCS3 expression in breast cancer cells was ascertained by evaluating SOCS3 content in the presence of FXR-DN plasmid." (PMID 26899873, 2016). "SOCS3 has been identified as an inducible suppressor of leptin signaling, and in breast cancer cells, its overexpression has been shown to decrease proliferation and anchorage-independent growth." (PMID 26899873, 2016). "Methylation of the SOCS3 promoter and reduced gene expression of SOCS3 have been documented in numerous tumors such as breast cancer, lung cancer, and liver cancer." (PMID 27516205, 2016). "In contrast, SOCS3 is detectable in breast cancer, and SOCS3 expression is increased during the development and progression of prostate cancer." (PMID 25849377, 2015). "Overall, this result is similar to recent data indicating an inverse relationship between SOCS3 expression and tumor stage and clinical outcome of breast cancer." (PMID 23028842, 2012). "In normal breast epithelial cells SOCS3 is induced, while in several breast cancer cell lines SOCS3 is weakly activated." (PMID 20553623, 2010).
breast cancer (continued). "In 8 samples of primary breast cancer, immunohistochemical staining of SOCS3 and 7 correlated with their respective mRNA expression." (PMID 20433750, 2010). "The present study is aimed to elucidate the clinicopathological features associated with SOCS1, SOCS2, SOCS3, CIS and IGF-I expression in breast cancer." (PMID 17651480, 2007). "The mRNA content of SOCS1, SOCS2 and IGF-I was assessed in 89 primary breast cancer samples, and of SOCS3 and CIS in 64 samples." (PMID 17651480, 2007). "SOCS-1 has been shown to be critical for preventing interferon γ (IFNγ)-mediated growth arrest of M-1 myeloid cells, and overexpression of SOCS-1 or SOCS-3 in breast cancer lines inhibits the antiviral and antiproliferative ability of IFNγ." (PMID 12888825, 2003). "Research shows that the expression levels of SOCS1, SOCS2, and SOCS3 are different in breast cancer tissue, which may be related to the heterogeneity of breast cancer tissue." (PMID 39307915, 2024). "SOCS3 may be a factor in the prognosis of breast cancer patients, while SOCS2 may be a potential therapeutic target." (PMID 39307915, 2024). "In addition, FOS activates Socs3 in different cell types, including pro-B lymphocytes, breast cancer cells, and NSC." (PMID 34359927, 2021). "Increasing evidence has suggested a role of SOCS3 in breast cancer as a regulator of STATs." (PMID 34120621, 2021). "Collectively, these findings indicate that a decrease in the expression of SOCS3 may promote the progression of breast cancer via the JAK-STAT signaling pathway and thereby worsen its prognosis." (PMID 34120621, 2021). "In addition, circTADA2As inhibits development and metastasis of breast cancer through targeting miR-203a-3p/SOCS3 axis." (PMID 32497020, 2020). "We have reported that the absence of SPTBN1 in hepatocellular carcinoma can activate Wnt pathways by downregulating kallistatin, while kallistatin increases apoptosis in breast cancer cells by inhibiting miR-203 and enhancing SOCS3 levels via PKC-ERK signaling." (PMID 32516133, 2020). "Furthermore, using ChIP and RNA immunoprecipitation, we examined the reciprocal regulation between DANCR and suppressor of cytokine signaling 3 (SOCS3) in breast cancer." (PMID 31860165, 2020). "MiRNA-203a-3p targets SOCS3 which inhibits breast cancer cell proliferation." (PMID 31597272, 2019). "Furthermore, SOCS3, a target gene of miR-203a-3p50, was downregulated in breast cancer tissues and was a good predictor for lymph node metastasis in breast cancer." (PMID 30787278, 2019). "Thus, CircTADA2A-E6 mediates miRNA-203a-3p/SOCS3-assisted inhibition of proliferation, migration, and invasion of breast cancer." (PMID 31597272, 2019). "Thus, SOCS3 suppression accelerated the IL-6-mediated growth and metastasis of mammary carcinoma via affecting myeloid differentiation in breast cancer." (PMID 30083161, 2018). "Thus, we concluded that the IL-6-related dysfunction of the SOCS3 feedback loop accelerated the growth and metastasis of mammary carcinoma by affecting myeloid differentiation and attenuating the T cell-based immune surveillance." (PMID 30083161, 2018). "Taken together, these data demonstrate that modulation of SOCS3 expression may represent a mechanism through which FXR activation could affect leptin activity on breast cancer." (PMID 26899873, 2016). "We further examined the expression of miR-203 and SOCS3 in limited breast cancer tissues." (PMID 27517632, 2016). "SOCS3 is known to be down-regulated in various types of cancers including breast cancer." (PMID 27517632, 2016). "However, breast cancer associated tumor suppressor genes such as RARRES1, SPARC, SOCS3, and LIF were also up-regulated in T47D cells." (PMID 25776849, 2015).
breast cancer (continued). "To evaluate the potential significance of SOCS expression in mammary carcinoma for prognosis and its association with clinicopathological characteristics we have investigated the mRNA levels of SOCS1, SOCS2, SOCS3 and CIS in a representative collection of primary breast cancers specimens." (PMID 17651480, 2007). "However, it is also possible that the initial decline in SOCS3 may be triggered by regional increases in intracellular calcium near the plasma membrane, as happens in breast cancer cells when PMCA2 levels are decreased." (PMID 38212474, 2024). "In addition, SOCS3 has previously been reported to be hypermethylated in melanoma, while loss of RAC3 expression has been associated with impaired invasion in glioma and breast carcinoma cells." (PMID 36125262, 2022). "Therefore, the precise roles of SOCS3 in breast cancer are still controversial, and this inconsistency in the findings may be due to the heterogeneity of breast cancer tissues." (PMID 34120621, 2021). "Therefore, inhibiting DANCR or up‐regulating SOCS3 may simultaneously target all three metastasis‐related phenotypes and improve the prognosis of breast cancer patients." (PMID 31860165, 2020). "Therefore, it will be essential to clarify that if SOCS3 deficiency and sustained activation of the JAK/STAT signaling pathway blocked the differentiation of myeloid progenitors and thus promoted e-MDSC development in breast cancer." (PMID 30083161, 2018). "However, sustained activation of the JAK/STAT signaling pathway was observed in breast cancer e-MDSCs because of significant SOCS3 suppression, which consequently induced the long-term activation of the NF-κB signaling pathway and suppression of T cell immunity." (PMID 30083161, 2018). "Therefore, it is urgent to elucidate the biological significance of SOCS3 deficiency in MDSC development and tumor progression, which may provide insight into potential therapeutic targets for breast cancer." (PMID 29326716, 2017). "Systemically, breast cancers remodel liver metabolism via signal transducer and activator of transcription 3 (STAT3)-suppressor of cytokine signaling 3 (SOCS3)-AMPK to create metastatic niches." (PMID 40725147, 2025). "The suppressor of cytokine signaling 3 (SOCS3) protein has been identified as the first potent biological inhibitor of PTK6, showing a tumor suppressive effect in T47D and MDA-MB-231 breast cancer cell lines." (PMID 37509364, 2023). "In breast cancer, it has been demonstrated that the polarisation of M2 macrophage was modulated by KLF14 via SOCS3/RhoA/ROCK signalling pathway, thereby suppressing tumour growth." (PMID 36178087, 2022). "Western blot analysis confirmed that pIRES2-SOCS2 transfection upregulated the expression of SOCS3 and reduced the levels of p-STAT3 and p-JAK in breast cancer cells." (PMID 34120621, 2021). "In breast cancer, IL-6 induces IDO production in MDSC by inhibiting the suppressor of cytokine signaling 3 (SOCS3), and inducing subsequent activation of the JAK/STAT signaling pathway." (PMID 34689842, 2021). "Therefore, understanding the mechanisms controlling DANCR expression during breast cancer development, effectively targeting these mechanisms, and developing strategies to either suppress DANCR or up‐regulate SOCS3 may prevent tumorigenesis and suppress the malignant progression of breast cancer." (PMID 31860165, 2020). "SOCS3 draws special attention by having three miR-205-5p binding sites and for being able to promoting growth, metastasis and EMT in breast cancer." (PMID 28346474, 2017). "IL-6 stimulated SOCS3 suppression and thus induced long-term activation of the JAK/STAT signaling pathway in breast cancer MDSCs." (PMID 29326716, 2017). "SOCS3 and SOCS1 expression has been widely investigated in a number of cancers, including breast cancer, multiple myeloma, hepatocarcinoma and lymphoma, where their absence suggests a tumor-suppressor function." (PMID 28445952, 2017).
breast cancer (continued). "In this study, we therefore sought to elucidate the relationship between pathological and clinical parameters and the expression of the SOCS family members SOCS1, SOCS2, SOCS3, and CIS in patients with breast cancer by RT-PCR." (PMID 17651480, 2007). "We determined the mRNA expression levels of SOCS1, SOCS2, SOCS3, CIS and IGF-I in 89 primary breast cancers by reverse transcriptase PCR." (PMID 17651480, 2007). "The SOCS3 gene is prognostic for renal cancer (unfavorable) and breast cancer (favorable) and reported to not be expressed in urothelial cancer (HPA)." (PMID 35039759, 2022). "miR-9 and miR-181a facilitates the development and immunosuppressive function of e-MDSCs through the interference with suppressor of cytokine signaling 3 (SOCS3) and protein inhibitor of activated STAT3 (PIAS3), separately, thus leading to immune escape and tumor growth in breast cancer." (PMID 36569895, 2022). "We report for the first time that DANCR essentially contributed to all three malignant phenotypes of breast cancer, which, on the molecular level, was mediated through EZH2‐controlled epigenetic regulation of suppressor of cytokine signaling 3 (SOCS3) via H3K27 trimethylation." (PMID 31860165, 2020). "Boosting SOCS3 expression may reverse the oncogenic activities of DANCR and thus provide a therapeutic strategy for breast cancer treatment." (PMID 31860165, 2020). "An additional role for the constitutively elevated CIS may be to decrease breast cancer sensitivity to interferons, similar to the decreased sensitivity to IFNγ seen in cutaneous T-lymphoma (CTCL) cell lines that constitutively express SOCS-3." (PMID 12888825, 2003). "Our previous work demonstrated that tumor exosomal miR-9 (targeting SOCS3) and miR-181a (targeting PIAS3) synergistically activate the JAK/STAT signaling pathway, driving MDSC expansion and suggesting novel intervention strategies for IL-6-driven breast cancer." (PMID 41281644, 2025). "SOCS3 overexpression revealed favorable effects in colorectal, ovarian cancer lines in MCF7 BC (Breast Cancer) cells and several solid tumors." (PMID 35455455, 2022). "SOCS3 may be a prognostic factor, and SOCS2 may be a potential therapeutic target in breast cancer." (PMID 34120621, 2021). "The exogenous expression of SOCS3 in MCF-7 cells increases the sensitization to cisplatin-mediated apoptosis, which implied that SOCS target therapeutic strategy may be helpful to overcome cisplatin resistance in breast cancer patients." (PMID 28228755, 2017). "This indicates that IL-6 trans-signaling is predominately mediated by soluble CD126 to regulate IL-6-dependent SOCS3 suppression and sustained activation of the JAK/STAT pathway in MDSCs, as well as coordinates the differentiation and immunosuppressive activity of MDSCs in breast cancer." (PMID 29326716, 2017). "In an analysis of 1109 breast cancer samples and 113 normal breast samples, SOCS2 and SOCS3 showed lower expression levels in cancer tissues than in normal tissues, and patients with high expression of SOCS2, SOCS3 and SOCS4 exhibited better outcome." (PMID 35884417, 2022).
hepatocellular carcinoma (49 papers, 2004 to 2025). A malignant tumor that arises from hepatocytes. "In this regard Ilangumaran and co-workers exhibited that hepatocellular carcinoma advances in SOCS1 deficiency through SOCS3-Dependent CDKN1A induction and NRF2 activation." (PMID 39286246, 2024). "Leptin induced STAT3 phosphorylation has also been shown to be inhibited by addition of adiponectin in hepatocellular cancer cells, which is associated with increased suppressor of cytokine signaling 3 (SOCS3) signaling, a negative regulator of STAT3." (PMID 29156726, 2017). "In addition, it has been shown that SOCS3 mRNA expression is significantly higher in HBV‐associated hepatocellular carcinoma (HCC) tissues." (PMID 36169255, 2022). "A decreased expression of SOCS3 is associated with advanced stage and poor prognosis of patients with hepatocellular carcinoma (HCC)." (PMID 35626153, 2022). "Similar to our findings in NPCs, high expression of SOCS3 inhibits migration in hepatocellular carcinoma and lung cancer cells." (PMID 36753521, 2023). "The binding of EYA2 and DACH1 transcriptionally regulates the expression of SOCS3 and inhibits the progression of hepatocellular carcinoma by blocking the activation of the SOCS3-mediated JAK/STAT signaling pathway." (PMID 36750914, 2023). "This is in line with observations that methylation at cg18181703 is negatively correlated with SOCS3 expression in hepatocellular carcinoma, arthritis, schizophrenia, and chronic hepatitis-B43." (PMID 37626025, 2023). "Hypermethylation of SOCS3 has been reported to contribute to hepatocellular carcinoma development and progression." (PMID 36674935, 2023). "SOCS1 and SOCS3 genes are considered tumor suppressors in hepatocellular carcinoma (HCC) due to frequent epigenetic repression." (PMID 32807134, 2020). "To investigate the role of PD-L1, CD4, CD8, CD276 and SOCS3 in Hepatocellular Carcinoma, we processed GSE102079 and GSE121248 datasets from Gene Expression Omnibus (GEO)." (PMID 32742491, 2020). "The aim of our study is to explore the regulation of C1QTNF1-AS1 on its target miR-221-3p/SOCS3 in human hepatocellular carcinoma (HCC)." (PMID 31222560, 2019). "Among the different systems the human hepatoma cell line HuH7 was most responsive with significant up-regulation of the genes coding for SOCS3, CXCL8 and mitogen activated protein kinases." (PMID 30547786, 2018). "A possible way to increase SOCS3 expression in HCC would be using adenoviral infection of hepatocellular carcinoma cells containing the SOCS3 gene." (PMID 28603644, 2017). "However, enforced expression of SOCS3 is proposed as a potential treatment for triple-negative breast cancer and hepatocellular carcinoma." (PMID 37775746, 2023). "Furthermore, a high rate of methylation was detected on several SOCS genes, such as SOCS1 in hepatocellular carcinoma, SOCS3 in head and neck squamous cell carcinoma, and SOCS6 in GC." (PMID 33937336, 2021). "Downregulation of miR-221 may promote the expression of its target gene SOCS3, which inhibits the proliferation, invasion, and migration of hepatocellular carcinoma cells by repressing the JAK-STAT3 signaling pathway." (PMID 32273831, 2020). "Previous findings indicated that GP130 signaling, induced by IL-6 ligands, may switch-off the responsiveness to IL-27, through the induction of the suppressor of cytokine signaling, SOCS3, in human hepatocellular carcinoma cells." (PMID 29020964, 2017). "SOCS3 may also be involved in the suppression of tumour growth and metastasis of several malignancies including malignant melanoma, lung cancer, hepatocellular cancer, and head and neck squamous cell carcinoma." (PMID 24757565, 2014). "HCV core protein induces SOCS3 expression in hepatoma cells, while it inhibits SOCS1 expression." (PMID 20862390, 2010).